IL34 (interleukin 34)
Diseases named in the same sentence as IL34 in open-access papers (continued):
Sharing a sentence is not in itself a finding about the gene and the disease.
tumor (continued). "IL-34 has been reported to be expressed in cancer cells and to promote tumor progression and metastasis of certain cancers via the promotion of angiogenesis and immunosuppressive macrophage differentiation." (PMID 33072227, 2020). "IL-34 and M-CSF were decreased > 40% and > 95%, respectively, in GC compared to tumour adjacent gastric tissues (p < 0.05), whereas CD68+-TAMs were increased 5.5 fold (p < 0.05)." (PMID 32765828, 2020). "Based on these results, it is strongly suggested that in vivo treatment with BET inhibitor JQ1 suppressed IL-34 expression in TME which leads to the anti-tumor effect." (PMID 33072227, 2020). "Our results are in accordance with previous studies and demonstrate that IL‐34 participate in tumor progression via the EMT phenotype in PTC cells." (PMID 32573824, 2020). "Although more detailed analysis by adding clinicopathological parameters and/or treatments of patients is necessary, the result implies a potential correlation between IL‐34 expression and tumor progression." (PMID 31417675, 2019). "Functional analyses of miR-28-5p revealed tumor suppressive properties caused by the inhibition of Rap1b, E2F6, IGF-1, IL-34, and AKT." (PMID 31921670, 2019). "Another regulating protein that seems to be capable of skewing the microenvironment into a tumor promoting direction is interleukin-34 (IL-34)." (PMID 30580386, 2019). "Compared with HBV‐negative adjacent tissues, HBV‐positive adjacent tissues and HBV‐negative HCC, the expression of IL‐34 was elevated in HBV‐related tumour tissues." (PMID 31621133, 2019). "Tissue samples from KPC mice and patients with PDAC were further stained with immunofluorescence antibodies to evaluate the presence of CSF1R ligands, CSF1, and interleukin-34 (IL-34) in the tumor microenvironment." (PMID 29719257, 2018). "We analyzed differential IL-34 gene expression of RNA-seq data from normal tissues and tumor tissues using data generated by The Cancer Genome Atlas (TCGA)." (PMID 29796177, 2018). "Another newly discovered cytokine IL-34 expressed by osteosarcoma cells sharing CSF-1R with CSF-1 recruited M2 macrophages, and its overexpression increased tumor growth, vascularization, and metastasis." (PMID 28197019, 2017). "Macrophages flocked to the tumour, the so-called tumour-associated macrophages (TAMs), are generally recruited by the activation of CSF1R by CSF-1 or IL-34, as well as by the chemokine CCL2." (PMID 28404796, 2017). "To further verify the relationship between IL34 and tumor cells, we localized tumor subgroups in the spatial transcriptome and found that the spatial location of the tumor with high IL34 expression was close to the TNF-α+ TAMs with high TNF and CCL2 expression." (PMID 39865310, 2025). "Additionally, deconvolution analysis of the BI group indicated a positive correlation between the predicted proportion of tumor cells and IL34 expression levels." (PMID 39865310, 2025). "Secreted IL34 was increased in the supernatant of Renca cells isolated from the latest passage (P6) compared with that of the parental (P0) cells and in the plasma of the serially passaged tumor-bearing mice." (PMID 40538439, 2025). "To validate this hypothesis, we performed multiplex immunofluorescence staining in tumor specimens and confirmed the proximal co-localization of IL34-positive tumor cells and TNF-α+ TAMs." (PMID 39865310, 2025). "However, this was mainly due to the role of IL34 in altering TAMs polarization toward the pro-tumor M2-type phenotype." (PMID 40538439, 2025). "In this scenario, CSF-1R ligands, IL-34 and M-CSF, play an important role in the crosstalk between immune and tumor cells, as, in fact, immune and cancer cells secreted cytokines and interleukins, which supported tumor development and progression." (PMID 38254773, 2024).
tumor (continued). "One particular mechanism of therapeutic interference was revealed when paclitaxel treatment of PyMT mice was shown to increase tumor cell secretion of CSF-1 and IL-34 and addition of a CSF-1R inhibitor to the treatment regime reduced tumor growth and rates of pulmonary metastasis." (PMID 39588367, 2024). "Furthermore, there was substantially more area of ROC from APF + IL-34 in predicting the incidence of HCC, compared to that from AFP alone, despite similar observed patterns between IL-34 + AFP vs tumor size, and AFP vs tumor size." (PMID 35347503, 2023). "In addition, significant inverse correlation was observed between IL-34 and differentiation or tumor size of HCC." (PMID 35347503, 2023). "In addition to its vital function in tumors, IL-34 has been identified as a factor that biases macrophages toward immunosuppression, leading to increased tumor evasion and progression." (PMID 36798830, 2023). "Substantial evidence has shown that IL-34, a cytokine first discovered to control the function and survival of monocytes/macrophages, is overexpressed in a wide variety of cancers, where it controls various tumor cell functions." (PMID 36798830, 2023). "Even though it is selectively expressed, IL-34 may be released by tumor cells, and it plays a crucial role in the development of tumors and their resistance to chemotherapy and molecularly targeted treatment." (PMID 36798830, 2023). "However, in the IL34-OC+Foxp3-anti group, the tumor volume was significantly smaller than in the IL34-OC+IgG group, and the number of lung metastatic foci was significantly lower." (PMID 38081923, 2023). "Nonetheless, it is worth noting that some studies suggest a beneficial role for IL-34 in particular tumor contexts, thus raising the question of whether the role of IL-34 in cancer is dependent on tumor type, location, or even treatment regimens." (PMID 36765929, 2023). "Here, studies suggesting that IL-34 may play a role in the development of therapeutic resistance to tumor-ICI therapies were summarized." (PMID 36798830, 2023). "IL-34 was associated with HBV-DNA, HBeAg, tumor differentiation and tumor size of HBV-HCC patients." (PMID 35347503, 2023). "IL-34 function is mainly mediated by interaction with the macrophage colony-stimulating factor-1 receptor (MCSF-1R), which is also over-expressed by CRC cells as well as by tumour-associated macrophages (TAMs) and cancer-associated fibroblasts." (PMID 35837402, 2022). "This could rely on the fact that additional compensatory mechanisms may limit the anti-tumor activity of IL-34/MCSF-1R blockers, including treatment-induced recruitment of regulatory T cells or myeloid-derived suppressor cells." (PMID 35837402, 2022). "Nonetheless, IL-34 is produced by many tumor cell types, including CRC cells." (PMID 35837402, 2022). "IL‐34 overexpression promoted tumor cell proliferation and chemoresistance." (PMID 35132816, 2022). "Consistent with this hypothesis, an anti‐IL34 antibody enhances anti‐PD‐1 therapy in a murine tumor model." (PMID 35132816, 2022). "Studies of IL-34 production by tumor cells in other cancer types indicates that aberrant expression of this growth factor cytokine can directly drive immune suppressive myeloid cells in their role in tumor resistance to T-cell directed checkpoint therapies." (PMID 35316296, 2022). "Although we cannot rule out that other cell types remaining in the PortalBMC cultures as possible sources of these factors, these data indicate that PDAC CTC can be a major contributor to the high concentrations of IL-34, M-CSF, GM-CSF, and IL-8 expression in the portal blood tumor microenvironment." (PMID 35316296, 2022). "In conclusion, IL‐34 expression in embryonal components may induce macrophage chemotaxis in a paracrine manner, and tumor cell proliferation and chemoresistance in an autocrine manner." (PMID 35132816, 2022). "In addition to promoting tumor metastasis, IL-34 can also inhibit tumor differentiation and migration." (PMID 34336646, 2021).
tumor (continued). "As IL-34 is related to tumor immune cells, we performed GO/KEGG/GSEA to explore whether pathways related to tumor immunity were enriched." (PMID 34336646, 2021). "The low concentration of M-CSF in the tumor CM also corroborates this hypothesis, and the effects seen with tumor CM alone could be due to another M-CSF receptor ligand (e.g., IL-34)." (PMID 34680504, 2021). "Taken together, these observations suggest that IL-34 may play an essential role in both the pro-tumorigenic polarization of TAMs, and tumor progression, as revealed in various other cancers." (PMID 33408768, 2021). "Interestingly, the average expression level of IL-34 in tumor samples was lower than that in samples around the tumors (P < 0.001)." (PMID 34336646, 2021). "Furthermore, the in vivo effects of juglone on IL-34-induced tumor development were studied in a BALB/c mice synergistic model with 4T1 cells." (PMID 33800170, 2021). "In tumor microenvironment, IL-34 mediates the interaction between tumor cells and TAM." (PMID 35096588, 2021). "IL-34 promotes tumor growth, metastasis, immune suppression, and therapeutic resistance." (PMID 33800170, 2021). "In our study, immune microenvironment analysis and GO and KEGG enrichment analyses showed that IL-34 expression was closely related to tumor immune responses and inflammation-related signaling pathways, which is consistent with the results from previous studies." (PMID 34336646, 2021). "Macrophages are an important part of the tumor microenvironment; therefore, regulation by IL-34 may have a certain effect on tumor microenvironment changes." (PMID 34336646, 2021). "Since IL-34 also regulates the function of inflammatory fibroblasts, we hypothesized that it could regulate the tumor promoting function of colorectal CAFs." (PMID 33260828, 2020). "IL-34 involvement in tumours is controversial, possibly due to the levels of M-CSF receptors." (PMID 32765828, 2020). "Therefore, blocking of IL-34 is considered as a promising therapeutic strategy to suppress tumor progression." (PMID 33072227, 2020). "Increased expression of IL‐34 has been found in patients with different kinds of carcinomas, including breast, lung, ovarian, and blood cancer, and it has been reported that its expression is correlated with the progression of tumor metastasis." (PMID 32573824, 2020). "Additionally, JQ1 treatment of mice bearing IL-34-producing tumor inhibited the tumor growth along with decreasing Il34 expression in the tumor." (PMID 33072227, 2020). "IL-34 also mediates the interaction between tumor cells and TAMs." (PMID 31968663, 2020). "IL-34 and M-CSF can induce macrophage polarization, mainly into the M2 phenotype, which subsequently leads to M2 macrophage mediated immunosuppression, promoting tumour progression and metastasis." (PMID 32765828, 2020). "In order to find possible candidates that could regulate IL-34 expression, we have at first taken a glance at transcriptional changes of IL34 in human cancer cell lines and a tumor tissue treated with several low molecular inhibitors." (PMID 33072227, 2020). "In the paracrine pathway, IL-34 produced by tumor cells and/or immune cells triggers M-CSF1-R signaling in tumor-associated macrophages (TAMs), thereby promoting recruitment of TAM to the tumor area, facilitating the formation of new blood vessels and the exosmosis of immunosuppressive cells." (PMID 33415105, 2020). "In the tumor microenvironment, IL-34 affects TAM functions in different ways." (PMID 31968663, 2020). "In the present study, we sought to ascertain whether IL-34 regulates the CAF-mediated tumor-promoting functions." (PMID 33260828, 2020). "We have demonstrated that decreased IL-34 in GC is inversely correlated with tumour differentiation, age and female gender of GC patients, which is consistent with others showing that younger, particularly female GC patients had more severe malignancy than older, male patients." (PMID 32765828, 2020).
tumor (continued). "Treatment of mice bearing IL-34-producing tumors with JQ1 shows anti-tumor effect." (PMID 33072227, 2020). "We here investigated whether, in CRC, tumor-associated macrophages (TAMs) express M-CSFR-1 and functionally respond to IL-34." (PMID 33298879, 2020). "We collected the tumor tissues at the endpoint of observation to analyze Il34 mRNA expression." (PMID 33072227, 2020). "Furthermore, IL‐34 expression in HBV‐related tumour tissues was higher than those in HBV‐positive adjacent tissues, HBV‐negative HCC and HBV‐negative adjacent tissues." (PMID 31621133, 2019). "M-CSF and IL-34 are cytokines that can regulate tumor-infiltrating macrophages." (PMID 30580386, 2019). "In addition to a modest reduction in tumor growth, aCSF1/-IL34 treatment modestly improved survival compared to control IgG recipients." (PMID 31552020, 2019). "IL-34 expression was distinctly separated between the normal and tumor tissues." (PMID 29796177, 2018). "The fact that IL-34 expression was enhanced by IFN-γ could appear inconsistent with the notion that IFN-γ stimulates anti-tumor adaptive immune response." (PMID 29423057, 2018). "There is also evidence that IL-34 plays a role in tumorigenesis given its ability to stimulate endothelial cell proliferation, vascular cord formation and recruitment of macrophages into the tumor tissue." (PMID 29423057, 2018). "CSF-1, CSF-1R, and IL-34 were weakly negatively associated with tumor purity, while the lack of association between immune cell infiltration and gene expression of PTPRZ1 and syndecan-1 was also reflected by tumor purity values." (PMID 29796177, 2018). "Several studies have shown a correlation between high IL-34 expression level and tumor development." (PMID 29796177, 2018). "Based on the mean Ct (cycle threshold) as a relative measure of the concentration of target in the PCR reaction, IL-34 gene expression was lower in cancer cell lines (mean Ct 30.94) as compared to our tumor samples (mean Ct 26.35) and normal tissue (mean Ct 26.26)." (PMID 29796177, 2018). "Recent studies showed a positive correlation between IL-34 expression and tumor development." (PMID 29423057, 2018). "Furthermore, CSF-1/CSF-1R also showed a higher correlation with tumor infiltrating lymphocytes (TILs) than IL-34, PTPRZ1, and syndecan-1." (PMID 29796177, 2018). "This suggests that the function of IL-34 in these tumors may be multidimensional, not only functioning as a tumor inhibitor or promoter." (PMID 25395235, 2015). "Moreover, IL-34-dependent CSF-1R activation increased the proliferative index of tumor cells." (PMID 38254773, 2024). "Furthermore, IL-34 produced by cancer cells is likely involved in MDSC-mediated tumor progression." (PMID 39457693, 2024). "While this phenotype might be associated with tumor immune escape, we hypothesized that the change from CSF1 to IL-34 could be important during the MFAP5 + fibroblasts mediated promotion of tumor malignancy through the driving of the immune evasive phenotype of C1QC + macrophages." (PMID 37344903, 2023). "However, the expression of IL-34 in LCC tumor tissues was significantly higher than in RCC." (PMID 35936748, 2022). "In the same way, immune cell infiltration in tumor regions was associated with CSF-1 and not IL-34." (PMID 33408768, 2021). "Also, we reported poor prognosis in patients with IL-34-expressing tumor." (PMID 33072227, 2020). "Moreover, inhibiting ERK signaling abolished the effect of IL‐34 on tumor progression." (PMID 32573824, 2020). "However, further works are warranted to better understand the favorable and deleterious effects of IL-34 in the tumor microenvironment, as well as to ascertain whether IL-34 is a valid biomarker for the diagnosis and management of cancer." (PMID 31968663, 2020).
tumor (continued). "We examined the expression of IL‐34 in serum and tissue samples of patients with PTC by Western blotting and ELISA assay and analyzed its association with clinicopathological features including tumor size, tumor node metastasis (TNM) stage, and lymph node metastasis (LNM)." (PMID 32573824, 2020). "Finally, molecules (e.g., cytokines) released within the tumor microenvironment by both immune and stromal cells may stimulate cancer cells to make IL-34." (PMID 31968663, 2020). "Moreover, IL-34 seems to educate TAMs to shape tumor-supportive immune niche." (PMID 31968663, 2020). "In the paracrine pathway, IL-34 produced by neoplastic cells and/or immune cells triggers the M-CSF1-R signaling in tumor-associated macrophages (TAMs), thus promoting their recruitment to the tumor area, favors the formation of new vessels, as well as the extravasation of immune-inflammatory cells." (PMID 31968663, 2020). "These tumor-related transcriptional factors may be involved in the effects of IL-34 in tumors." (PMID 25395235, 2015). "However, studies on the role of IL-34 in tumor development are limited." (PMID 25395235, 2015). "The distinct coexpression patterns of IL34 and CSF1R suggest their involvement in tumour progression, immune suppression, and potentially macrophage polarisation." (PMID 41362277, 2026). "We set out to conduct a detailed spatial analysis of human CIN3 samples, focusing on the complex interplay between immune cells and the tumour microenvironment, particularly the role of IL34 and CSF1R in tumour progression, as proposed in previous research." (PMID 41362277, 2026). "In osteosarcomas under sheer stress, tumour derived IL34 increases TAM recruitment exacerbating NA/VM, tumour growth and metastasis." (PMID 40442778, 2025). "First, due to the pleiotropic roles of IL34, which depend on the cellular and molecular context of the TME, it is not surprising that IL34 can have different functions in different types of tumor." (PMID 40538439, 2025). "Reduced gastric IL-34 promotes tumour growth by recruiting TAM2 cells to the GC mucosa via M-CSF, fostering a tumour-permissive environment." (PMID 40416985, 2025). "The activation of the CSF-1R by its ligands, colony-stimulating factor 1 (CSF-1) and Interleukin-34 (IL-34), regulates TAM polarization towards an immunosuppressive M2 phenotype, promoting tumor progression and immune evasion." (PMID 39457693, 2024). "CSF-1R ligands, IL-34 and M-CSF, are produced by many cells in the tumor microenvironment (TME), suggesting a key role for the receptor in the crosstalk between tumor, immune and stromal cells in the TME." (PMID 38254773, 2024). "The axis with IL-34/M-CSF/M-CSFR is useful for regulating macrophage differentiation and thus influencing tumor progression." (PMID 38159254, 2023). "In the therapeutic models’ cellular components of the TME, IL-34 was shown to alter the cellular profiles and the inflammatory state of the TME in the tumor." (PMID 36798830, 2023). "IL‐34 blocking abrogated the TAM infiltration in murine HM‐1 and CT26 tumor model and increased the infiltration of NOS2‐positive M1‐like TAMs,44 and this suggested IL‐34 was also involved in M2‐polarization of TAMs." (PMID 35132816, 2022). "A further mechanistic investigation is underway by our group to elucidate the functional role of IL34 in HAMP expression and tumor progression." (PMID 36532749, 2022). "There is a positive correlation between intra-hepatic IL-34 and the size of HCC, when the tumor size is smaller than 5 cm, but an inverse correlation with HCC if the tumor size is >5 cm." (PMID 36438052, 2022). "Then RNA was extracted from tumor tissue, and qRT-PCR showed that the expression of NEAT1, IL-34, VEGFA, SPINK1, S100A14, and P4HA2 was downregulated and the expression of CCNE2 was upregulated in NEAT1 knockdown tumor tissue." (PMID 36213831, 2022).